BMP5 (bone morphogenetic protein 5)
Description:
Growth factor of the TGF-beta superfamily that plays essential roles in many developmental processes, including cartilage and bone formation or neurogenesis. Initiates the canonical BMP signaling cascade by associating with type I receptor BMPR1A and type II receptor BMPR2. In turn, BMPR1A propagates signal by phosphorylating SMAD1/5/8 that travel to the nucleus and act as activators and repressors of transcription of target genes. Can also signal through non-canonical pathway such as MAPK p38 signaling cascade to promote chondrogenic differentiation. Promotes the expression of HAMP, this is repressed by its interaction with ERFE.
Tractability: Antibody: UniProt places it where antibodies can reach, with medium confidence; UniProt predicts a signal peptide or a membrane-spanning region; its Gene Ontology location is reachable by antibodies, with medium confidence.
Gene: Protein-coding gene on chromosome 6 (55,753,653 to 55,875,595, reverse strand). Ensembl gene ENSG00000112175.
Subcellular location: Secreted
Gene Ontology:
Molecular function: BMP receptor binding; protein binding; cytokine activity; growth factor activity
Biological process: BMP signaling pathway; negative regulation of aldosterone biosynthetic process; negative regulation of cell population proliferation; negative regulation of cortisol biosynthetic process; negative regulation of insulin-like growth factor receptor signaling pathway; negative regulation of steroid biosynthetic process; positive regulation of cell population proliferation; positive regulation of dendrite development; positive regulation of epithelial cell proliferation; positive regulation of SMAD protein signal transduction; positive regulation of transcription by RNA polymerase II; type B pancreatic cell development; allantois development; cardiac muscle tissue development; cardiac septum morphogenesis; chorio-allantoic fusion; endocardial cushion formation; heart development; heart trabecula morphogenesis; hindbrain development; negative regulation of epithelial to mesenchymal transition; negative regulation of extrinsic apoptotic signaling pathway via death domain receptors; negative regulation of mononuclear cell migration; neural fold elevation formation; pericardium morphogenesis; and 6 more
Cellular component: extracellular region; vesicle
Genetic constraint (gnomAD): Loss-of-function variants: 22 observed, 44.18 expected, observed/expected ratio (o/e) 0.5, 90% interval 0.35 to 0.71. The upper end of that interval is the gene's LOEUF score, 0.71, which puts it in group 2 of 6, group 1 being the genes least tolerant of losing a copy. Missense variants: 535 observed, 583.23 expected, observed/expected ratio (o/e) 0.92, 90% interval 0.85 to 0.99. Synonymous variants: 203 observed, 200.48 expected, observed/expected ratio (o/e) 1.01, 90% interval 0.9 to 1.14.
Homologues: Orthologues: chimpanzee BMP5 (100% identical), macaque BMP5 (100% identical), rabbit BMP5 (98% identical), dog BMP5 (98% identical), pig BMP5 (97% identical), guinea pig BMP5 (94% identical), rat Bmp5 (94% identical), mouse Bmp5 (93% identical), tropical clawed frog bmp5 (81% identical), zebrafish bmp5 (77% identical). Paralogues in human: BMP7 (63% identical), BMP6 (60% identical), BMP8B (46% identical), BMP8A (46% identical), BMP2 (26% identical), BMP4 (26% identical), GDF6 (25% identical), GDF2 (24% identical), GDF5 (24% identical), BMP10 (23% identical), GDF7 (21% identical), TGFB3 (20% identical), and 19 more.
Diseases named in the same sentence as BMP5 in open-access papers:
BMP5 is named in the same sentence as 69 diseases in open-access papers, as found by Europe PMC text mining. Sharing a sentence is not in itself a finding about the gene and the disease. The quoted sentences say what the papers report.
breast carcinoma (18 papers, 2013 to 2025). "Conversely, BMP5’s lower diagnostic efficacy raises questions about its functional role in breast cancer, necessitating further investigation into its mechanistic pathways." (PMID 41403941, 2025). "Another highly expressed gene in NTF2 high dox + cells was BMP5, a gene whose downregulation in breast cancer is associated with disease recurrence." (PMID 34880267, 2021). "The inquisition reports that lower BMP5 mRNA expression was associated with lower overall survival rate in breast cancer and lung cancer." (PMID 31973134, 2020). "The highest mutation was found in the R321*/Q amino acid of BMP5 corresponding to colorectal and breast cancer whereas the alteration frequency was higher in lung squamous carcinoma datasets (>4%)." (PMID 31973134, 2020). "In particular, BMP5 appears to be closely associated with breast cancer." (PMID 35054776, 2022). "Unlike colorectal cancer, where miR-32-5p directly targets PTEN/BMP5 to drive metastasis, our work reveals a breast cancer-specific mechanism: miR-32-5p suppresses FBXW7, stabilizing c-MYC." (PMID 40711670, 2025). "BMP2, BMP4, GDF11 and TGFBR2 had relatively higher levels in bone metastases of breast cancer while BMP5, BMP7, BMPR2, BMPR1A and ACVR2A presented lower expression in the bone metastases, in the E-MTAB-4003 dataset." (PMID 37333824, 2023). "Increased expression of BMP5 following G9a depletion tended to improve the prognosis and suppress the metastasis of breast cancer." (PMID 35054776, 2022). "Breast cancer patients with low BMP5 expression showed poor survival outcomes compared to those of patients with high BMP5 expression." (PMID 35054776, 2022). "In summary, this study provides novel insights into the tumor-suppressive characteristics of G9a mediated by the modulation of BMP5 expression in breast cancer cell lines." (PMID 35054776, 2022). "BMP5, as a tumor suppressor, has been previously studied in myeloma, adrenocortical carcinoma, breast cancer, and colorectal cancer." (PMID 34745928, 2021). "Analysis of TCGA datasets through UALCAN and GEPIA database also exhibited similar BMP5 expression in breast carcinomas, colorectal adenocarcinomas, lung squamous cell and adenocarcinomas, bladder cancer and glioblastomas." (PMID 31973134, 2020). "The loss of BMP5 seems to be an early event in CRC initiation and development, on the contrary a significant increase of BMP5 positive rate has been found in breast carcinoma in comparison to normal tissues suggesting that the role of BMP5 varies among tumors." (PMID 32664456, 2020). "Several studies have demonstrated that BMP5 functions as tumor suppressor in myeloma, adrenocortical carcinoma, and breast cancer." (PMID 30572883, 2018). "While BMP5 positive rate is significantly higher in breast carcinoma than normal tissues, which is consistent with the copy number amplification tested in public data." (PMID 30572883, 2018). "Our breast cancer findings suggest that c-MYC targeting represents a novel therapeutic axis distinct from BMP5/PTEN pathways, potentially offering unique advantages in hormone receptor-positive breast cancers where c-MYC dysregulation drives proliferative signaling." (PMID 40711670, 2025). "Furthermore, we suggested that BMP5 is a novel target of G9a, which is responsible for modulating the growth and metastasis of breast cancer cells." (PMID 35054776, 2022). "Similarly, low BMP5 levels were found in breast cancer patients and correlated with cancer recurrence." (PMID 35054776, 2022). "Treatment with recombinant BMP5 reduced the migration/invasion capabilities of breast cancer cells." (PMID 35054776, 2022). "Therefore, we aimed to identify G9a-mediated changes in BMP5 expression and the resultant regulatory role of these changes in breast cancer growth and metastasis." (PMID 35054776, 2022). "Moreover, reduction in the migration/invasion ability of MCF7 and T47D breast cancer cells was induced by BMP5." (PMID 35054776, 2022).
breast carcinoma (continued). "Interestingly, our microarray analysis indicated that BMP5 is a putative target gene regulating G9a-induced tumor aggressiveness; however, few studies have documented the relationships between G9a and BMP5 in breast cancer." (PMID 35054776, 2022). "Additionally, several studies demonstrated that BMP5 functions as a tumor suppressor in myeloma, adrenocortical carcinoma, and breast cancer." (PMID 34680590, 2021). "In addition, Romagnoli M revealed that BMP5 was repressed by Blimp-1 during EMT process via TGF-β1 in breast cancer and that the poor prognosis of breast cancer was associated with BMP5 low expression." (PMID 33123277, 2020). "In the case of breast cancer, BMP5 expression was low using ONCOMINE, UALCAN, and GEPIA database." (PMID 31973134, 2020). "In addition, BMP-5 mRNA levels in breast cancer cell lines and in primary breast tumors were lowered when compared with normal tissues, and correlated with cancer recurrence." (PMID 32050622, 2020). "However, later studies showed a positive correlation of BMP5 down-regulation with lower relapse-free survival in breast cancer patients and can be used as a therapeutic strategy combined with TGFβ1 to reduce cellular proliferation." (PMID 31973134, 2020). "It has been reported that TGF-β1 induced EMT via repression of BMP5 in breast cancer." (PMID 33092068, 2020). "This difference in genetic alteration, especially in that of colon and breast cancer may suggest that the role of BMP5 varies among tumors." (PMID 30572883, 2018). "BMP5 has been previously studied in myeloma, adrenocortical carcinoma, and breast cancer." (PMID 30572883, 2018). "In breast cancer, amplification of BMP5 may act as a passenger, thus promote the advanced tumor progression." (PMID 30572883, 2018). "Thus, whether the G9a-knockdown-induced increase in BMP5 expression influences Smad1/5/9 phosphorylation in breast cancer cells needs to be elucidated." (PMID 35054776, 2022). "BMP5 can reduce proliferation in PANC-1 cells but the role of BMP5 in breast cancer is unknown." (PMID 23577196, 2013). "We examined the clinical correlation of four key genes (PSMB8, BCL2, BMP5, and PSME2) with breast cancer prognosis." (PMID 41403941, 2025). "The TCGA-BRCA breast cancer dataset exhibits separate Kaplan–Meier survival curves (KM) for four notable genes (PSMB8, BCL2, BMP5, and PSME2)." (PMID 41403941, 2025). "BMP7, GDF15, BMP5, SMAD6 and FSTL5 were highly expressed in the ER positive breast cancer cells (MCF-7 cells), while the expressions of TGFBR2, FSTL1 and NOG were reduced in this cohort." (PMID 37333824, 2023). "In breast cancer, Blimp-1 plays an inevitable role in TGF-β1 mediated epithelial-to-mesenchymal transition (EMT) through the suppression of BMP5 expression." (PMID 31973134, 2020). "In breast cancer, TGF-β1-induced epithelial-to-mesenchymal transition is mediated by Blimp-1-dependent repression of BMP-5." (PMID 32050622, 2020). "In breast cancer, GSE19615 and GSE12276 datasets showed that patients with lower BMP5 expression (n = 13 and 43, respectively) had significantly lower overall survival compared to patients with higher BMP5 expression (n= 102 and 161, respectively)." (PMID 31973134, 2020). "In contrast, the over-expression of BMP5 was observed in lung adenocarcinoma (LUAD), and breast cancer." (PMID 31973134, 2020). "BMP8B was significantly active in primary breast cancer, while BMP2, BMP4, BMP5, BMP6, BMP8B were significantly active in liver metastasis." (PMID 31557971, 2019). "To investigate a potential involvement of the BMP family in telomerase activity, we examined the effects of BMP2, BMP4, BMP5, BMP6 and BMP7 on telomerase activity by spiking the medium of cultured human breast cancer MCF-7 cells with purified recombinant human cytokines." (PMID 27696331, 2017).
colorectal cancer (13 papers, 2017 to 2025). A primary or metastatic malignant neoplasm that affects the colon or rectum. "In colorectal cancer, miR−ـ32ـ5p functions as an oncogene by targeting BMP5 and is linked to lymph node metastases and distant dissemination." (PMID 40711670, 2025). "Mutated BMP5 proteins were profiled in 11 cases of breast and colorectal cancers, whereas only a single missense mutation was reported in ovarian cancer." (PMID 31973134, 2020). "Previous studies on colorectal cancer showed a significant correlation between BMP5 down-expression and mutation and the prognostic value of colorectal cancer (CRC), triggering the initiation and development of tumors." (PMID 31973134, 2020). "These overall data-driven results suggest that apart from one alteration in colorectal cancer, low expression of BMP5 is associated with poor prognosis in breast, colorectal, lung and bladder cancer." (PMID 31973134, 2020). "This study revealed mutations in breast invasive ductal and colorectal carcinoma in a hotspot at position R321*/Q and position V5A/L/S in lung squamous carcinoma between BMP5-propeptide and BMP5 domain." (PMID 31973134, 2020). "Moreover, the Kaplan Meier-plot and PrognoScan showed that low expression of BMP5 is associated with poor prognosis in bladder, breast, lung, and colorectal cancer compared to the prognosis in ovarian cancer." (PMID 31973134, 2020). "MiR-32 has been recognized as an oncopromotor in colorectal cancer owing to its capacity to target BMP5." (PMID 40711670, 2025). "We selected BMP5 as a putative target gene, since it has recently been reported to impede the migration/invasion of colorectal cancer cells and act as a tumor suppressor." (PMID 35054776, 2022). "In two recent reports, miR-32 was shown to promote tumorigenesis, radioresistance, migration, and invasion of colorectal cancer by targeting BMP5 and TOB1." (PMID 34938324, 2021). "The mean results of the analysis of the current investigation suggest the role of BMP5 as tumor suppressor gene in colorectal cancer." (PMID 31973134, 2020). "In the digestive system, BMP-5 plays similar roles in both colorectal cancer (CRC) and pancreatic cancer." (PMID 32050622, 2020). "As previous studies reported that BMP5 inhibits cell proliferation in several tumor entities, we investigated the influence of BMP5 on colorectal cancer cell growth." (PMID 30572883, 2018). "At the epigenomics level (methylation), an earlier study on colorectal cancer confirmed that the methylation alteration on BMP3 or BMP5 may trigger the malignant transformation of normal cells." (PMID 35155435, 2022). "BMP5 is considered as an early event in colorectal cancer, with prognostic value, related with a coexpression pattern with E-cadherin and could be considered tissue-specific." (PMID 34073426, 2021). "In colorectal cancer, miR-32-5p primarily targets BMP5 (Bone Morphogenetic Protein 5), a tumor suppressor involved in TGF-β signaling and epithelial-mesenchymal transition regulation." (PMID 40711670, 2025). "Expression of BMP2, BMP4, BMP5, BMP6, BMP9 and osteocalcin has been reported in colorectal cancer with heterotopic ossification." (PMID 29029440, 2017). "Unlike prior studies in prostate or colorectal cancers, where miR-32-5p targets BMP5 or PTEN, our work proposes c-MYC as a potential downstream effector in MCF-7 cells, offering a novel therapeutic axis." (PMID 40711670, 2025).
osteoarthritis (10 papers, 2009 to 2026). A noninflammatory degenerative joint disease occurring chiefly in older persons, characterized by degeneration of the articular cartilage, hypertrophy of bone at the margins and changes in the synovial membrane. "In osteoarthritis, a chronic inflammatory disease affecting bone joints, BMP5 has been found to regulate chondrocyte growth through the ERK/p38 signaling pathway." (PMID 40705171, 2025). "In this study, we using the in vivo destabilization of the medial meniscus (DMM) mouse model to investigate the role of bone morphogenetic protein 5 (BMP5) in osteoarthritis (OA) progression mediated via chondrocyte senescence and apoptosis." (PMID 33744859, 2021). "BMP4 and BMP5 are downregulated in osteoarthritis, rheumatoid arthritis, and systemic lupus erythematous." (PMID 32139667, 2020). "In the other hand, BMP5 accelerates expression of hypertrophy markers which is of relevance in both development and diseases such as osteoarthritis, this is consistent with the presence of higher values in OA patients macerates against OP ones." (PMID 23351916, 2013). "Among the genes with the peak expression in the mid-pregnancy followed by a drop at term, BMP5, CDH11 and FST are implicated in bone and cartilage related disorders such as rheumatoid arthritis and osteoarthritis." (PMID 23145134, 2012). "In synovial tissue of patients with osteoarthritis and rheumatoid arthritis, the expression of BMP-5 was decreased." (PMID 21403850, 2011). "BMP, a crucial member of the TGF-β superfamily, has been extensively studied for its function in regulating osteoarthritis in mice, as well as proliferation and apoptosis of TD broiler chondrocytes treated with 100 mg/kg thiram, specifically involving its ligands BMP5/6/7-related peptides." (PMID 41035230, 2026). "Our data suggest that PS77 may be a potential therapeutic agent for osteoarthritis by downregulating BMP5 and DLX5, thereby suppressing the expression of pro-inflammatory cytokines." (PMID 40705171, 2025). "However, BMP5 downregulation was reported to decrease chondrocyte apoptosis in an osteoarthritis disease model, reflecting a context-dependent role for BMP5 in cell survival." (PMID 40471239, 2025).
adrenocortical carcinoma (6 papers, 2015 to 2021). "Down-regulation of BMP-5 mRNA expression was found in tissue samples from adrenocortical carcinoma and adrenocortical tumor cell lines when compared with normal adrenal glands." (PMID 32050622, 2020). "In adrenocortical carcinoma, BMP-5 was likely to be involved in the modulation of the malignant and functional phenotype of adrenocortical cancer cells." (PMID 32050622, 2020). "The expression of BMP5 is down-regulated under highly vascularized conditions, like those simulated by tumor cell lines (i.e., adrenocortical carcinoma and adrenocortical tumor cell lines)." (PMID 26445145, 2015).
lung carcinoma (6 papers, 2018 to 2024). "Another BMP5 mRNA expression (RNA Seq V2) analysis via cBioPortal web found a higher mutation rate in lung cancer and then in bladder cancers." (PMID 31973134, 2020). "Apart from HAND1, BMP3 together with BMP5 has been considered potential multi-omics level lung cancer biomarkers according to recent publications." (PMID 35155435, 2022). "Although a study based on 76 lung cancer samples initially found that BMP5 was downregulated, the prognostic value and potential function of BMP5 in lung adenocarcinoma are still unclear." (PMID 34745928, 2021). "In our query, EDNRB is shown to be co-expressed with BMP5 in bladder, breast, colorectal and lung cancer." (PMID 31973134, 2020). "ACVR2A, ACVR1C, BMP4, and CHRDL2, on the other hand, was found to be commonly co-expressed with BMP5 in bladder, breast and lung cancer." (PMID 31973134, 2020). "In lung cancer, BMP5 is a common gene but it is downregulated, as are TGF-β receptors and SMADs; therefore, none of them may be involved in the regulation of SOX4 and DLX5 expression." (PMID 39228892, 2024). "In view of the critical role of EGFR and STK11 mutations in the efficacy of lung cancer treatment, we analyzed the differences of BMP5 mRNA expression in patients with and without EGFR and STK11 mutations." (PMID 34745928, 2021). "Our results demonstrated that metformin drug resistance increases the expression of proinflammatory and invasive genes, including BMP5, CXCL3, VCAM1, and POSTN, in A549 lung cancer cells." (PMID 37239373, 2023). "Finally, we identified BMP5 as having significantly differential expression and superior prognostic value, rather than BMP2, BMP4, and BMP7, which have been extensively explored in lung cancer." (PMID 34745928, 2021). "However, for gastrointestinal cancer and lung cancer that with high incidence and mortality rate worldwide, the intensive study of BMP5 has not been investigated yet." (PMID 30572883, 2018).